INS (insulin)
Diseases named in the same sentence as INS in open-access papers (continued):
Sharing a sentence is not in itself a finding about the gene and the disease.
type 1 diabetes (continued). "Despite this, the effects of exercise and insulin therapy on diabetic rat cortical bone may be of clinical relevance because of the evident osteopenia and risk for fracture in patients with type 1 diabetes." (PMID 34440530, 2021). "In its early stage (Stage 1), type 1 diabetes is usually asymptomatic; however, the development of autoimmunity is often detectable in early life, with circulating autoantibodies targeting insulin or other proteins, such as GAD65, insulinoma-associated protein 2 (IA­2) or zinc transporter 8 (ZNT8)." (PMID 33595677, 2021). "Type 1 diabetes is a chronic disease caused by the inability of the pancreas to produce insulin." (PMID 34300672, 2021). "Although rs2227982 may not be a functional PD-1 SNP, previous studies on east Asians reported correlations with the risk of type 1 diabetes, with glucose and insulin levels after the oral glucose tolerance test, and with ankylosing spondylitis." (PMID 34206082, 2021). "In cases of poor control, patients with insulin-deficient, type 1 diabetes may present with increased plasma triacylglyceride (TAG) levels and ketoacidosis." (PMID 33667544, 2021). "This included differences in bacterial diversity and richness, and an increased abundance of Bacteroides dorei in children with the susceptible INS genotype, a finding that is consistent with the increased abundance of Bacteroides dorei in children who developed type 1 diabetes in a Finnish study." (PMID 33515070, 2021). "In addition, muscle loss is associated with the deficiency of insulin and C-peptide in type 1 diabetes." (PMID 34722893, 2021). "Type 1 diabetes is a chronic autoimmune disease characterised by insulin deficiency due to pancreatic beta cell loss, which leads to hyperglycaemia and lifelong dependence on exogenous insulin." (PMID 34023962, 2021). "Recent pre-clinical studies suggested that loss of insulin signalling may contribute to atrial electrical remodelling and atrial fibrillation in murine models of type 1 diabetes." (PMID 33482830, 2021). "Insulinoma may mask the existence of type 1 diabetes or cause recurrent hypoglycemia and decreased insulin requirement in a type 1 diabetic patient." (PMID 34583764, 2021). "An absolute deficiency of insulin secretion causes type 1 diabetes (T1D)." (PMID 34631003, 2021). "Besides glycometabolic assessment and adequate insulin dosage adjustment, type 1 diabetes needs prompt recognition of potentially associated autoimmune conditions." (PMID 34438593, 2021). "Diabetes type 1 arise from an autoimmune reaction caused by the body ́s immune cells destroying the pancreases beta cells responsible for insulin production resulting in a relative or absolute deficiency of insulin as the pancreases produces very little to none of the hormone." (PMID 34422158, 2021). "Indeed, a defect in this process (e.g., loss of insulin expression) is the earliest event in the pathogenesis of autoimmune diseases such as type 1 diabetes (T1D)." (PMID 33672010, 2021). "In a rat model of type 1 diabetes, a mild neuropathy with inflammatory components could be induced by insulin treatment causing an abrupt reduction in HbA1c." (PMID 34639176, 2021). "Autoimmunity against insulin often appears in genetically susceptible children aged 9 months to 3 years, with a peak incidence at 9–12 months of age, and this loss of immune tolerance to insulin often leads to type 1 diabetes." (PMID 33515070, 2021). "Our principal finding in the present study corroborates the hypothesis that the rapid fall in HbA1c upon insulin-induced normoglycaemia may be the main causative factor of TIND in type 1 diabetes." (PMID 33557206, 2021). "Type 1 diabetes (T1D) is a metabolic disease characterized by chronic hyperglycemia, resulting from defective production of insulin due to the selective destruction or loss of functional insulin-producing β cells through an autoimmune process occurring in genetically predisposed individuals." (PMID 34067388, 2021).
type 1 diabetes (continued). "Results from the present study indicate that at transcriptomic level reduction in OXPHOS, DNA repair and inflammation-related genes is linked to better insulin sensitivity and protection against microvascular complications in persons with long-term type 1 diabetes." (PMID 34671071, 2021). "We and others have demonstrated that in humans with type 1 diabetes, a condition of insulin deficiency, serum concentrations of ucOC are positively associated with insulin exposure, either exogenously administered or endogenously produced, as assessed by c-peptide levels." (PMID 32483283, 2020). "Moreover, in insulin-deficient mice and those with type 1 diabetes (T1D), blood betatrophin concentrations were significantly elevated." (PMID 32076603, 2020). "The cause of diabetes type I is death of insulin-producing pancreatic β-cells." (PMID 33209247, 2020). "According to the hypothesis, excessive body weight in a child who is predisposed genetically to the development of type 1 diabetes accelerates the process of beta cell destruction leading to an earlier occurrence of an overt deficit of insulin." (PMID 31990164, 2020). "The hallmark of type 1 diabetes (T1D) is T cell-mediated autoimmune destruction of pancreatic beta cells, leading to insulin deficiency, elevated blood glucose concentrations, and life-long need for exogenous insulin therapy." (PMID 33153010, 2020). "Moreover, type I diabetes is also caused by the progressive destruction of pancreatic insulin-producing β cells, which can be damaged by lipids entering and accumulating in this organ." (PMID 32630448, 2020). "Type 1 diabetes is an autoimmune disease that results from the specific loss of insulin-secreting pancreatic beta cells leading to severe insulin deficiency and the requirement for insulin replacement therapy." (PMID 32314012, 2020). "We observed a fraction of blood plasma extracellular vesicles positive for membrane proteins potentially associated with insulin-producing beta-cells and identified differentially expressed extracellular vesicles derived miRNAs in individuals with type 1 diabetes." (PMID 32296701, 2020). "These factors have effects on insulin secretion and Type 1 diabetes risk." (PMID 32815547, 2020). "Generating insulin-producing cells (IPCs) from human pluripotent stem cells is a promising method for studying the molecular mechanism underlying pancreas development and a potential treatment source for type 1 diabetes." (PMID 32541687, 2020). "Akita mice are genetically engineered species susceptible to develop type 1 diabetes; this genetic engineering involves mutations in the insulin genes, which cause accumulation of misfolded insulin protein in pancreatic β-cell, leading to diminished insulin secretion capacity and type I diabetes." (PMID 32566684, 2020). "Screening for islet autoantibodies is performed in people with a genetic predisposition for type 1 diabetes to investigate the natural history of the disease and when enrolling patients into interventional trials aimed at delaying the requirement for insulin replacement therapy." (PMID 31286933, 2019). "A Finnish population study reports that 10% of women with a previous GDM develop type 1 diabetes within 6 years; the risk for type 1 diabetes correlates with an age under 30 years, with the need for insulin therapy during pregnancy, and with a positivity for at least 1 antibody." (PMID 31053128, 2019). "One theory proposes that type 1 diabetes may be caused by an autoimmune response while the immune system attacks virus-infected insulin-producing cells in the pancreas." (PMID 30863376, 2019). "Other type 1 diabetes-associated regions that contribute are the INS, IL21 and CTSH gene regions." (PMID 31438962, 2019). "Type 1 diabetes is an autoimmune disease with progressive destruction of pancreatic beta-cells triggered by a genetic predisposition combined with environmental factors, resulting in a deficiency in insulin production." (PMID 31156453, 2019).
type 1 diabetes (continued). "This might be due to the fact that all type 1 diabetes patients are put on insulin therapy which has a higher risk of iatrogenic hypoglycemia." (PMID 30700277, 2019). "Notably, prospective studies have shown that circulating unmethylated INS DNA is positively associated with the development of type 1 diabetes." (PMID 31428654, 2019). "From gestational week 11 to week 16, there is a minor decrease in insulin requirements as a consequence of an improvement in insulin sensitivity that is known to increase the risk of especially nocturnal hypoglycaemia in women with type 1 diabetes." (PMID 31828161, 2019). "Insulin-reactive B cells escape immune tolerance in mice susceptible to type 1 diabetes." (PMID 31444529, 2019). "The hallmark of type 1 diabetes is the deterioration of endogenous insulin secretion." (PMID 30919585, 2019). "High-affinity IAAs are generally more predictive of type 1 diabetes and were found to be associated with the disease appearance at a young age, subsequent progression to multiple autoantibody positivity, and binding to human insulin A chain residues 8–13." (PMID 31827651, 2019). "The HypoDeg trial will compare treatment with insulin degludec to insulin glargine U100 in terms of risk of nocturnal hypoglycaemic episodes in patients with type 1 diabetes with the greatest potential to benefit from near-physiological insulin replacement therapy." (PMID 31337371, 2019). "Foods with a low GI cause a smaller increase in the glucose level, reducing the peak of glycemia, but at the same time it was demonstrated that such foods increase the risk of hypoglycemia after the meal in people with type 1 diabetes if taken with inadequate doses of insulin." (PMID 30871141, 2019). "Type 1 diabetes (T1D) is characterized by chronic autoimmune mediated destruction of pancreatic β-cells, leading to symptomatic partial, or in most cases, absolute insulin deficiency requiring lifelong administration of exogenous insulin." (PMID 30915320, 2019). "The primary aim is to test the hypothesis that treatment with insulin degludec as compared to insulin glargine U100 results in lower risk of symptomatic nocturnal hypoglycaemia in patients with type 1 diabetes and high risk of severe nocturnal hypoglycaemia." (PMID 31337371, 2019). "Sulfatide is known to participate in the regulation of first-phase insulin secretion and it is possible that the observed loss of pancreatic sulfatide may contribute to the loss of first-phase insulin secretion seen during the development of type 1 diabetes." (PMID 29671030, 2018). "Type 1 diabetes is caused by autoimmune destruction of pancreatic β cells in genetically predisposed individuals and results in severe insulin deficiency with a requirement for treatment with insulin." (PMID 29199115, 2018). "If not occurring by chance, it may reflect the weight loss often seen in individuals with type 1 diabetes prior to diagnosis as a consequence of insufficient insulin production." (PMID 29589073, 2018). "Type 1 diabetes (T1D) is a prototypic tissue-specific autoimmune disease characterized by lymphocytic infiltration into the islets of Langerhans, resulting in loss of insulin-producing β cells and hyperglycemia." (PMID 30687564, 2018). "This study aimed to evaluate whether autoantibodies against N-terminally truncated GAD65 more closely defined a type 1 diabetes phenotype associated with insulin therapy." (PMID 29619531, 2018). "Thus, perhaps ketones, in addition to serving other roles, act to preserve muscle mass in insulin-reduced or -deficient states, such as untreated type 1 diabetes, fasting, or a ketogenic diet." (PMID 30071599, 2018). "Automated insulin delivery systems can potentially modify insulin dosing in response to activity monitors to reduce the risk (or severity) of exercise-induced hypoglycemia in people living with type 1 diabetes." (PMID 30530451, 2018).
type 1 diabetes (continued). "The excessive use of insulin that is often required to achieve glycaemic control in type 1 diabetes increases susceptibility to severe hypoglycaemia and may lead to some measure of hyperinsulinemia." (PMID 29596460, 2018). "Hyperglucagonemia in type 1 diabetes may be caused by the total loss of insulin secretion, and of its inhibitory effect on α-cells." (PMID 29416045, 2018). "Emphasis is also placed on the emerging (and somewhat surprising) consensus that the extent of beta cell loss is variable among people with type 1 diabetes and that many (especially those who are older at onset) retain significant numbers of insulin-producing cells long after diagnosis." (PMID 30255378, 2018). "The deficiency of insulin and elevation of glucocorticoids in patients with type 1 diabetes may lead to increased Enpp1 expression, resulting in the accumulation of PPi." (PMID 29513794, 2018). "First-phase insulin response in intravenous glucose tolerance tests is compromised in children with multiple biochemical islet autoantibodies independently of HLA-conferred risk of type 1 diabetes." (PMID 29300921, 2018). "Weinvestigated whether insulin affects renal Nrf2 expression in type 1 diabetes (T1D)and studied its underlying mechanism." (PMID 28324005, 2017). "The additional benefit of closed-loop insulin delivery in individuals with well controlled type 1 diabetes (ie, HbA1c <7·5%) is the reduction of the residual risk of complications, hypoglycaemia, and glycaemic variability, as well as the burden of self-management." (PMID 28094136, 2017). "Residual endogenous insulin secretion in patients with type 1 diabetes is associated with improved long-term glycemic control, reduced risk of severe hypoglycemia, reduced risk for the development of diabetic retinopathy and improved statural growth in prepubertal children." (PMID 28459844, 2017). "The authors hope that the findings reported herein may serve as a benchmark for implementing insulin therapy in patients with type 1 diabetes while simultaneously minimizing the risk for hypoglycemia." (PMID 28683068, 2017). "Type 1 diabetes is a progressive autoimmune disease caused by infiltration of autoreactive lymphocytes in the islets of Langerhans which, ultimately, will destroy the insulin-producing β-cells." (PMID 28356069, 2017). "Type 1 diabetes was previously known as insulin-dependent, juvenile or childhood-onset diabetes, and it is characterized by deficient insulin production that requires daily administration of insulin." (PMID 28729836, 2017). "Type I diabetes is associated with deficiency of insulin due to autoimmune-mediated β cells damage." (PMID 29387011, 2017). "And this may be the case although patients were treated with insulin, which is a causal treatment in type 1 diabetes and may thus attenuate the chronic impact of systemic metabolic derangements in type 1 diabetics on the heart." (PMID 27999359, 2016). "Type 1 diabetes (TD1) is caused by insufficient insulin production by the pancreas β-cells." (PMID 28231175, 2016). "Type 1 diabetes mellitus (T1D) is an autoimmune disease characterized by infiltration of leukocytes into the islets of the pancreas, resulting in progressive pancreatic β-cell destruction and loss of insulin production." (PMID 28024918, 2016). "Once again, it is important to consider the fact that the lack of cardiac dysfunction may be related to permanent treatment with exogenous insulin, which is a causal treatment in type 1 diabetes." (PMID 27999359, 2016). "Apoptosis is the major cause of death of insulin-producing beta- cells in type 1 diabetes." (PMID 27203422, 2016). "Type 1 diabetes is caused by the destruction of insulin producing beta cells by the immune system." (PMID 26783747, 2016). "Type I diabetes is caused by loss of insulin-secreting beta cells." (PMID 27973548, 2016).
type 1 diabetes (continued). "Regular physical activity in individuals with type 1 diabetes is associated with several health benefits, including improved fitness and quality of life, improved insulin sensitivity, reduced lipid levels, and lower rates of micro- and macrovascular complications and mortality." (PMID 27287376, 2016). "Thus, recently, the issues of insulin peroral intake by children at high risk for type 1 diabetes via daily oral administration of 67.5 mg of insulin, compared with placebo, resulted in an immune response without hypoglycemia." (PMID 26221192, 2015). "Studies of the rs9729 polymorphism are rare, but one paper reported that a haplotype contained rs9729 in a German population was negatively associated with type 1 diabetes, an autoimmune disease that results in T cell-mediated destruction of insulin-producing cells within the pancreas." (PMID 26177022, 2015). "Besides age and gender we found body composition, insulin dose, urinary protein, and glycemic control related to adiponectin levels in type 1 diabetes, some with persistent association across age and duration and others stronger at longer duration." (PMID 25950008, 2015). "These direct actions of insulin may also contribute to the association of type 1 diabetes and endometrial cancer, as mediated through the effects of exogenous insulin administration." (PMID 26134033, 2015). "The cause of type 1 diabetes (T1D) is widely considered to involve the interaction of environmental exposures with a common genetic predisposition leading to the autoimmune destruction of the insulin-secreting beta cells in the pancreas." (PMID 25884839, 2015). "Mutations at INS lead to neonatal diabetes, type 1 diabetes, and hyperinsulinemia." (PMID 25102180, 2014). "This work describes the metabolic changes associated with insufficient insulin administration in the type 1 diabetic rat kidney, showing that poor glycemic control with insufficient insulin administration, has an cumulative effect on the development of late diabetic complications." (PMID 25501426, 2014). "Both islet transplantation and islet-like cells could be used in type 1 diabetes, which is caused by autoimmune destruction of pancreatic insulin producing β-cells." (PMID 25405207, 2014). "The only clear risk factor for diabetes type 1 (the insulin group) seemed to be a family member's serious or chronic illness, which may point to the hereditary nature of the illness in the Finnish population." (PMID 24868461, 2014). "We herein provide evidence that metabolic alterations in the α-cell model of insulinopenic diabetes may lead to a paradoxical glucagon response, which would thereby lead to glycemic instability in insulin-deficient type 1 diabetes." (PMID 25393115, 2014). "The results showed that patients treated with ≥ 4 injections/day or insulin pump were in the highest and middle level of dietary adherence and concluded that greater dietary adherence was associated with lower A1c among youth with type 1 diabetes." (PMID 24607084, 2014). "Clinical trials have shown that the use of insulin analogs or pumps may be associated with a reduced risk of nocturnal or daytime hypoglycemia in patients with type 1 diabetes, while achieving good metabolic control." (PMID 25289645, 2014). "Type 1 diabetes (T1D) is caused by autoimmune destruction of insulin-producing islet β cells." (PMID 23390544, 2013). "Type 1 diabetes is a condition that results from the loss of insulin-producing β-cells." (PMID 24204325, 2013). "Type 1 Diabetes (T1D) is considered to be a T-helper- (Th-) 1 autoimmune disease and is characterised by a lack of insulin, which is caused by the autoimmune destruction of insulin-producing pancreatic beta cells." (PMID 23841104, 2013). "Thus the vasodilatory and antioxidant effects of insulin are depressed in case of insulin deficiency (i.e. type 1 diabetes)." (PMID 24355617, 2013).